MIR337 (microRNA 337)
Synonyms: hsa-mir-337; MIRN337; mir-337
Gene: MicroRNA gene on chromosome 14 (100,874,493 to 100,874,585, forward strand). Ensembl gene ENSG00000199151.
Gene Ontology:
Biological process: cellular response to glucose stimulus; long-term synaptic potentiation; miRNA-mediated post-transcriptional gene silencing
Cellular component: RISC complex
Homologues: Orthologues: chimpanzee ptr-mir-337 (100% identical), macaque MIR337 (98% identical), guinea pig MIR337 (95% identical), mouse Mir337 (90% identical), rat Mir337 (90% identical).
Diseases named in the same sentence as MIR337 in open-access papers:
MIR337 is named in the same sentence as 1 disease in open-access papers, as found by Europe PMC text mining. Sharing a sentence is not in itself a finding about the gene and the disease. The quoted sentences say what the papers report.
infection (1 paper, 2021). The state of being infected such as from the introduction of a foreign agent such as serum, vaccine, antigenic substance or organism. "BCG infection of lung epithelial A549 cells led to >10 times greater expression of MIR337-3p at 12 h after infection compared to medium control." (PMID 34912331, 2021). "Together, the data above suggest that while mycobacterial infection induces high-level MIR337-3p/Mir337-3p, MIR337-3p/Mir337-3p can promote the mycobacterial entry/infection and replication/growth in host target cells." (PMID 34912331, 2021). "Similarly, BCG infection of macrophage THP-1 and RAW264.7 cells resulted in six and eight times greater expressions of MIR337-3p/Mir337-3p, respectively, at 12 h after infection." (PMID 34912331, 2021).